INS (insulin)
Diseases named in the same sentence as INS in open-access papers (continued):
Sharing a sentence is not in itself a finding about the gene and the disease.
diabetes (continued). "People with diabetes (PwD) have abnormal levels of insulin in their bodies, causing their glucose levels to fluctuate uncontrollably." (PMID 37631595, 2023). "Some medications, such as insulin and sulfonylureas, which are used to treat diabetes can increase the risk of hypoglycemia." (PMID 37998569, 2023). "Core-shell insulin/vildagliptin-loaded nanofibers extend the drug delivery of insulin and vildagliptin and accelerate the repair of wounds associated with diabetes." (PMID 37168611, 2023). "Zinc has been associated with obesity and diabetes in recent research, particularly in terms of altered lipid and insulin profiles, oxidative stress, inflammatory processes, insulin resistance, obesity, and serum leptin levels." (PMID 36846698, 2023). "Diabetes (defined as fasting blood glucose equal to or above 7 mmol/L) is a chronic metabolic disease caused by insulin abnormalities and manifested as an increase in blood glucose." (PMID 36839280, 2023). "ICA69 is first identified as a diabetes-associated protein well characterized for its function in the biogenesis of secretory vesicles and trafficking of insulin from ER, Golgi to post-Golgi in pancreatic beta cells." (PMID 37251649, 2023). "Clinical cross-sectional study of patients with Type 2 diabetes mellitus indicated that lower fasting and postprandial glucagon-to-insulin ratio was significantly associated with the presence of NAFLD." (PMID 36942499, 2023). "Diabetes and reduced insulin sensitivity are associated with reduced striatal dopamine and an 80% increased likelihood of developing Parkinson’s disease, a disease characterized by motor deficits due to dopaminergic neuron loss in the basal ganglia." (PMID 37034167, 2023). "Diabetes is associated with abnormal carbohydrate, fat, and protein metabolism due to defects in insulin secretion, insulin action, or both." (PMID 37238803, 2023). "Conversely, epidemiological and experimental data show that low-GI diets can reduce the risk of these diseases, improve blood glucose control and insulin sensitivity in people with diabetes, reduce high blood fat levels, and can be useful for weight control." (PMID 36875857, 2023). "Diabetes mellitus (DM) is a metabolic disease caused by deficient insulin secretion or impaired insulin action, resulting in abnormal blood glucose levels." (PMID 37242519, 2023). "Type 1 diabetes mellitus (T1D) is an autoimmune disease associated with the eradication of insulin-producing pancreatic β cells, chronic hyperglycemia, and many other pathological changes." (PMID 37305057, 2023). "In people at higher risk of developing diabetes, such as those with overweight/obesity, defective early insulin secretion and delayed insulin responses lead to frequent postprandial subclinical hypoglycemia." (PMID 37367911, 2023). "Vanadium administration was found to alleviate several diabetes-related metabolic changes while offering two advantages over insulin: it is orally active and seems to avoid the risk of hypoglycemia." (PMID 37958659, 2023). "Diabetes after TP is characterized by the complete deficiency of insulin, pancreatic glucagon, and pancreatic polypeptide." (PMID 36860372, 2023). "Hyperinsulinemia condition in patients with diabetes is associated with impaired blood vessels due to oxidative pressure and inflammation influenced by the high amount of insulin level in the blood." (PMID 37903815, 2023). "According to the recently revised diagnostic criteria for SPIDDM, the interval from diabetes diagnosis to the requirement of insulin treatment is >3 months." (PMID 37373160, 2023). "Isolated human islets from carriers of the RREB1 coding allele that is associated with lower diabetes risk (p.Asn1171) had lower glucose-stimulated insulin secretion." (PMID 36633628, 2023). "Depression and cognitive deficits are more common in people with diabetes, possibly because insulin resistance disrupts the dopaminergic systems implicated in both depression and memory." (PMID 37034167, 2023).
diabetes (continued). "Branched-chain amino acid (BCAA) synthesis was upregulated: increased BCAA concentrations are found in various insulin-deficient and -resistant states, especially diabetes and obesity." (PMID 37138260, 2023). "Diabetes is characterized by hyperglycemia caused by defects in insulin secretion, insulin action, or both." (PMID 36721144, 2023). "Diabetes mellitus is one of the most common metabolic diseases that is caused by an absolute or relative deficiency in insulin secretion and/or insulin action." (PMID 36935499, 2023). "Diabetes is a metabolic disorder usually caused by insufficient secretion of insulin from the pancreas or insensitivity of cells to insulin, resulting in long-term elevated blood sugar levels in patients." (PMID 37957549, 2023). "Elevated blood glucose levels are a hallmark of diabetes mellitus, which includes a variety of biological processes, including insulin secretion, insulin resistance, and glucose absorption." (PMID 36983154, 2023). "Abnormal leptin, adiponectin, and insulin levels are associated with obesity, diabetes, and other metabolic disorders." (PMID 36829148, 2023). "As Robert Sargis discussed in “Environmental Drivers of Diabetes Risk, Complications, and Disparities,” a variety of EDCs, from both natural and synthetic origin, can alter insulin secretion and action and disrupt glucose homeostasis." (PMID 38229904, 2023). "In particular, type 2 diabetes mellitus has multiple causes, and the symptoms are severe due to β-cell inactivation, insulin resistance, and inflammatory responses due to environmental factors (obesity, dietary habits, lack of exercise) and genetic factors." (PMID 37111730, 2023). "Diabetes mellitus (DM), commonly referred to as diabetes, is a chronic metabolic disorder caused by insufficient insulin production and/or insulin resistance resulting from both environmental and genetic components." (PMID 37223032, 2023). "Type 1 diabetes mellitus causes a deficiency of insulin due to autoimmune or genetic disorders, while type 2 diabetes (T2D) generates an insulin resistance or reduced insulin sensitivity as a result of inappropriate diet or lack of physical activity." (PMID 36770385, 2023). "A hallmark of diabetes is the progressive destruction of β-cells within the pancreatic islets, leading to insulin production deficiency, hyperglycemia, and metabolism breakdown." (PMID 37195917, 2023). "Glycogen synthase kinase 3 (GSK-3) activity has been shown to be higher in insulin resistant tissues, thus causing impaired insulin action, and further resulting in high expression of glycogen synthase in diabetes." (PMID 38096150, 2023). "The biological plausibility for a possible association between diabetes, subclinical and overt hypothyroidism is explained by hyperglycemia linked to impaired insulin secretion and also with insulin resistance." (PMID 36669424, 2023). "Diabetes mellitus (DM) is a chronic metabolic disorder caused by an alteration in insulin secretion, insulin action or both." (PMID 37038362, 2023). "Lactobacillus, Roseburia, Bacteroides, and Akkermansia reduced the risk of diabetes by inhibiting pro-inflammatory factors and maintaining intestinal barrier integrity, improving glucose metabolism and insulin sensitivity." (PMID 37108143, 2023). "Clinical characteristics of patients identified to have this mutation include a family history of diabetes, glucose intolerance, and past or current insulin therapy." (PMID 37175989, 2023). "DMT2 is the most common type of diabetes (more than 95% of all cases), and it is caused by insulin resistance and defective insulin secretion due to pancreatic β-cell dysfunction." (PMID 36766803, 2023). "Most often, pancreatic beta cell dysfunction or injury causes anomalies in insulin action and production, which results in the development of diabetes." (PMID 36838577, 2023).
diabetes (continued). "After the first discovery of insulin by researchers in 1922, it was widely believed that the cause of diabetes was entirely due to insufficient insulin secretion." (PMID 37089923, 2023). "Diabetes is caused by an imbalance in carbohydrate, protein, and lipid metabolism as a result of complete or partial insulin secretion and/or activity." (PMID 36974247, 2023). "Streptozotocin has been previously reported to induce diabetes by causing the death of pancreatic β cells by alkylation of DNA, reducing insulin synthesis and release." (PMID 37754257, 2023). "For people with diabetes, hypoglycemia is caused by excess insulin action in the setting of impaired counterregulation." (PMID 37942482, 2023). "Apparently, infected patients who are at risk for diabetes or who have a history of type 2 diabetes and use insulin would require more frequent admission to intensive care." (PMID 36983573, 2023). "T2D is the most prevalent kind of diabetes in the general population, and is frequently caused by inadequate insulin production or insulin resistance." (PMID 36904097, 2023). "Diabetes is thought to be caused by several factors, such as impaired insulin production, impaired insulin physiological activity, and inflammatory response." (PMID 37457185, 2023). "We demonstrated that a positive family history of diabetes, overweight or obesity and the need for insulin treatment are associated with GDM recurrence." (PMID 36595021, 2023). "Abnormally high concentrations of plasma lipids in diabetes are mainly due to an increase in the mobilization of free fatty acids from the peripheral depots in the absence or deficiency of insulin." (PMID 35237941, 2023). "Taken together, these data suggest that insulin action in intestinal epithelial cells plays a protective role against the development of hepatocellular carcinoma associated with diabetes and NASH." (PMID 37852976, 2023). "A diagnosis of diabetes was recorded for 184 individuals (69.7%), 147 (55.7%) had an HbA1c level in the diagnostic range for diabetes (mean 54.6 mmol/mol), and 125 (47.3%) self-reported use of insulin." (PMID 36329166, 2023). "Diabetes is mainly caused by insufficient insulin secretion and is mainly treated by insulin or glucagon-like peptide-1 (GLP-1) analogs and other drugs." (PMID 36770503, 2023). "Since insulin is a pivotal hormone that regulates blood sugar, IR is closely associated with all stages of DM, including prediabetes, diabetes, and its complications." (PMID 37056675, 2023). "Diabetes mellitus (DM) refers to a metabolic disease characterized by chronic hyperglycemia due to impaired insulin secretion and/or utilization from multiple causes." (PMID 36721171, 2023). "American Association of Clinical Endocrinologists (AACE) and American Diabetes Association (ADA) recommend basal-bolus insulin instead of slide-scale insulin for glycemic control due to its effectiveness and safety." (PMID 38008775, 2023). "Type 1 diabetes mellitus, a T cell-mediated autoimmune disease characterized by the destruction of insulin-producing β cells and loss control of blood glucose, lacks effective treatment so far35." (PMID 37907476, 2023). "Diabetes (diabetes mellitus, DM) is a metabolic disease characterized by chronic hyperglycemia resulting from pancreatic β-cell dysfunction and peripheral insulin resistance caused by genetic and environmental factors." (PMID 38283742, 2023). "Triterpenes show significant promise in improving β-cell damage caused by diabetes by influencing various genes and proteins associated with insulin signaling, inflammation, oxidative stress, and apoptosis." (PMID 38003949, 2023). "Further, 40 mg/kg streptozotocin administration to HFD-fed rats cause β-cells necrosis, resulting in deficiency of insulin and development of diabetes." (PMID 37089941, 2023).
diabetes (continued). "miRNAs play a crucial role in the regulation of multiple pathways implicated in diabetes pathogenesis, such as insulin secretion, insulin signaling, beta cell function, and glucose homeostasis." (PMID 37560309, 2023). "Another RCT compared high-versus low-Glycemic Index nutritional interventions, including 156 adults at risk of insulin-independent diabetes for 3 months." (PMID 38201865, 2023). "Insulin signaling in the hippocampus has been targeted to improve impaired cognitive activity associated with diabetes mellitus and obesity (Fernandez and Torres-Alemán, 2012)." (PMID 37025701, 2023). "It is worth noting that insulin secretagogues are usually prescribed to young adult patients (i.e., patients with pre-diabetes or a new diagnosis of T2D) due to the enhanced risk of hypoglycemia in aged people." (PMID 36902770, 2023). "Diabetes mellitus is associated with an increase in cardiovascular risk due to the impaired insulin sensitivity caused by excessive lipid concentrations in the cells." (PMID 37894680, 2023). "Evidence from epidemiological, clinical, and neuropathology has shown that patients with diabetes are at higher risk of developing AD due to impaired brain insulin signaling." (PMID 37434738, 2023). "Type 1 diabetes mellitus (T1D) is a chronic disease caused by the destruction of insulin-producing pancreatic β-cells by cytotoxic immune cells." (PMID 38139149, 2023). "Diabetes is a chronic metabolic disease caused by a reduction in the production and/or action of insulin, with consequent development of hyperglycemia." (PMID 36946851, 2023). "The roles of age at onset of disease, insulin use and diabetes’ complications in their association were also analyzed." (PMID 36804018, 2023). "Diabetes mellitus is a metabolic disorder that is typically characterized by the loss of the ability of β-pancreatic cells to adequately produce and secrete insulin, leading to hyperglycemia." (PMID 37958667, 2023). "Regular physical activity can reduce diabetes risk by enhancing energy expenditure, insulin action through increased muscle glucose uptake, and muscle insulin sensitivity." (PMID 37310512, 2023). "Achieving optimal glycemic control and improving insulin sensitivity are crucial in mitigating the risk of diabetes-related complications." (PMID 37308493, 2023). "A meta-analysis of 18 studies with 12,277 patients with diabetes and COVID-19 reported that insulin was significantly associated with increased risk of mortality." (PMID 36418578, 2023). "Associations and HRs were consistent when analyses were adjusted for baseline age, gender, diabetes duration, HbA1c, insulin use, and CV risk." (PMID 37017470, 2023). "A significant antagonistic regulator of the insulin signaling pathway among them is the protein tyrosine phosphatase 1 B (PTP-1 B) associated with diabetes." (PMID 36838577, 2023). "The aim of this study is to examine the sex-specific association of T2DM with dementia subtypes, and to examine the roles of age at onset of disease, insulin use and diabetes’ complications in their association." (PMID 36804018, 2023). "Contrary to BPA, few studies have shown in vivo that phthalates/DEHP are linked to diabetes interfering with insulin secretion." (PMID 36901966, 2023). "Diabetes is a metabolic disease characterized by elevated levels of blood glucose caused by impaired capability to produce or respond to insulin." (PMID 37891184, 2023). "Type 1 diabetes mellitus (T1DM) is a complex metabolic disease characterized by a massive loss of insulin-producing cells due to an autoimmune reaction." (PMID 36829683, 2023). "Our study provides potent new tools for studying insulin signaling, physiology and mechanisms underlying development of insulin resistance, and diseases like diabetes mellitus." (PMID 36730473, 2023). "Rare genomic variants within INS and other genes have recently been identified to elevate odds for T1D and neonatal/monogenic diabetes." (PMID 36830626, 2023).
diabetes (continued). "Biguanides, sulfonylureas/glucosidase inhibitors, and oral hypoglycemic agents such as thiazolidinedione and insulin are used to treat diabetes; however, they cause gastrointestinal side effects such as abdominal pain, diarrhea, and nausea." (PMID 37754257, 2023). "There is limited evidence regarding the association between insulin response in diabetes in Asian populations and serum 25-hydroxyvitamin D3 (25[OH]D3) insufficiency." (PMID 34588362, 2023). "This study showed a convincing inverse linear association of MD with insulin-independent diabetes mellitus." (PMID 38201865, 2023). "Insulin therapy was associated with worse diabetes self-management compared to oral antidiabetic use, diet, and physical activity, and combined medical therapy." (PMID 36809582, 2023). "It is described as “hyperglycaemia” caused by deformities in insulin secretion, insulin activity, or both." (PMID 38106650, 2023). "Of the components included in the diabetes severity score, insulin use was the most significant factor related to the risk of TB, followed by CKD." (PMID 37041513, 2023). "Even though diabetes is regarded as a metabolic disorder, exogenous insulin dependency is typically caused by the autoimmune destruction of insulin-producing cells of the pancreas in type 1 diabetes (T1D)." (PMID 37346038, 2023). "One cell type of interest is the pancreatic insulin-producing β cell whose loss and/or dysfunction leads to diabetes." (PMID 36964318, 2023). "T1DM accounts for about 5% of diabetes cases and is caused by insulin deficiency due to the apoptosis or loss of insulin-secreting pancreatic β-cells destroyed by the autoimmune system." (PMID 37765234, 2023). "Several participants linked overeating to a specific macronutrient, namely carbohydrates, thereby continuously underlining the connection to the diabetes:“I have eaten more carbohydrates than the carbohydrates I have taken insulin to cover." (PMID 36754894, 2023). "A mixed strategy, only using ACC sometimes when insulin dosing for meals, was associated with the lowest empowerment score and highest HbA1c and should warrant extra education and support from the diabetes team to reinforce a dosing strategy." (PMID 38004219, 2023). "Diabetes mellitus is a metabolic disorder characterized by high blood sugar levels or hyperglycemia, which is caused by abnormalities in insulin secretion, insulin resistance, or both." (PMID 37372155, 2023). "Diabetes mellitus (DM) is a condition related to a deficiency in the hormone insulin, as seen in Type 1 DM, or associated with the development of insulin resistance, as seen in Type 2 DM." (PMID 37374145, 2023). "Type 1 diabetes mellitus is caused by genetic or autoimmune destruction of insulin-producing islet beta cells and accounts for 5-10% of total diabetes cases." (PMID 37867511, 2023). "Research has verified that smoking contribute to the higher risk of diabetes by 44%, as it triggers insulin resistance and inadequate insulin secretion, and amplifies the incidence of abdominal obesity." (PMID 37849795, 2023). "Insulin clearance by the liver is a long-recognized phenomenon that is now being revaluated as a possible factor in diabetes risk." (PMID 36904127, 2023). "Diabetes mellitus (DM) is characterized by persistent hyperglycemia caused by insulin resistance and/or impairment in insulin production by pancreatic beta cells." (PMID 37761200, 2023). "Diabetes mellitus (DM) is a group of metabolic diseases characterized by hyperglycemia caused by inadequate or impaired insulin secretion or utilization." (PMID 36935502, 2023). "Diabetes mellitus, as a metabolic disease, is an increase in blood glucose levels due to reduced insulin secretion or defective insulin action caused by a variety of etiological factors, including genetics and environment." (PMID 38053727, 2023). "Diabetes affects the body’s ability to metabolize sugars, which is caused by either insufficient insulin production or resistance to insulin." (PMID 37947589, 2023).